MRPS23 (mitochondrial ribosomal protein S23)
Diseases named in the same sentence as MRPS23 in open-access papers (continued):
Sharing a sentence is not in itself a finding about the gene and the disease.
cancer (9 papers, 2017 to 2026). A tumor composed of atypical neoplastic, often pleomorphic cells that invade other tissues. "Of the MRPSs associated with more than one cancer type, MRPS23 has been the most well-studied, however studies have found a conflicting role for the protein within and between cancer types." (PMID 39354291, 2024). "Our study utilized the MRPS23 role in human diverse cancer, and we clarified the association between MRPS23 expression and stem cell, RNA modification regulators expression, in human cancer." (PMID 38301044, 2024). "Of the five that have been associated with multiple cancer types, MRPS23 presents as an interesting candidate for further study." (PMID 39354291, 2024). "The authors hypothesized that overexpression of MRPS23 could be the link explaining the association between abnormal mitochondrial function and the development of cancer." (PMID 34440674, 2021). "Here, our study reveals that MRPS7 and MRPS23 critically stabilize β-catenin by inhibiting its ubiquitination, thereby promoting β-catenin-mediated cancer stemness and EMT in NPC." (PMID 41522354, 2026). "The correlation between RNA modification regulators and MRPS23 in cancer was assessed using the TCGA TARGET GTEx." (PMID 38301044, 2024). "MRPS23 expression level had high correlation with the stroma score in 25 types human cancer, the microenvironment in 27 types cancer, the 38 types of immune cells in 32 types cancer, and the immune score in 24 types cancer." (PMID 38301044, 2024). "We revealed the relationship between MRPS23 expression and RNA modification regulators of pan-cancer." (PMID 38301044, 2024). "ROC curve analysis indicated that MRPS23 is expected to be used as a biomarker for the diagnosis of pan-cancer with high specificity and sensitivity." (PMID 38301044, 2024). "Our research also indicated MRPS23 expression level is in relation to the stem cell, infiltration of immune cells, m1A, m5C and m6A in human cancer." (PMID 38301044, 2024). "A previous study reported that the expression of mitochondrial ribosomal protein S23 (MRPS23) is altered in several cancer types." (PMID 34440674, 2021). "MRPS23 was reported to be overexpressed in various cancers, such as breast, ovarian, colorectal, uterine leiomyoma and hepatocellular carcinoma." (PMID 29069745, 2017). "In 30 kinds of cancers, the expression of MRPS23 was highly correlated with 6 major immune cells." (PMID 38301044, 2024). "MRPS23 expression was markedly correlated with m1A, m5C and m6A in many types of cancers." (PMID 38301044, 2024). "However, the MRPS23 role in pan-cancer diagnosis, prognosis, stem cell, RNA modification, and immune regulation remains unclear." (PMID 38301044, 2024). "This suppression led to the inhibition of EMT and cancer stem cell properties, highlighting the cooperative role of MRPS7 and MRPS23 in NPC pathogenesis." (PMID 41522354, 2026). "Collectively, these findings position MRPS7 and MRPS23 as critical upstream modulators that orchestrate β-catenin-dependent control of two fundamental oncogenic programs in NPC: EMT progression and cancer stem cell maintenance." (PMID 41522354, 2026). "Given the critical role of EMT and cancer stemness in mediating chemoresistance and metastatic dissemination, we sought to further elucidate the functional contributions of MRPS7 and MRPS23 to these clinically relevant phenotypes." (PMID 41522354, 2026). "Mitochondrial ribosomal protein S23 (MRPS23), a component of the ribosome small subunit, has been reported to be overexpressed in various cancers and has been predicted to be involved in increased cell proliferation." (PMID 38301044, 2024). "Currently, no studies have tested whether MRPS23 is associated with cancer prognosis." (PMID 38301044, 2024). "Compared with MRPS23, the functional role of MRPS7 in cancer remains poorly characterized." (PMID 41522354, 2026).
cancer (continued). "Collectively, our findings reveal that MRPS7 and MRPS23 serve as critical cooperative regulators in the progression of NPC progression, orchestrating a network of oncogenic processes that encompass cellular migration, EMT, and the maintenance of cancer stemness." (PMID 41522354, 2026).
mitochondrial disease (4 papers, 2016 to 2024). "Genomic variants in MRPS23 have previously been associated with mitochondrial disease, and the data presented here strongly support a mitochondrial diagnosis." (PMID 39288270, 2024). "We identified 37 novel mutations in known mitochondrial disease genes and 3 mitochondria-related genes (MRPS23, QRSL1, and PNPLA4) as novel causative genes." (PMID 26741492, 2016). "We identified 3 novel disease-causing mitochondria-related genes (MRPS23, QRSL1, and PNPLA4) as well as other disease-causing genes and novel pathogenic mutations in known mitochondrial disease-causing genes." (PMID 26741492, 2016). "Mitochondrial disease-causing mutations were found in thirteen small ribosomal subunit mitoribosomal proteins (MRPS1, MRPS2, MRPS6, MRPS7, MRPS9, MRPS11, MRPS14, MRPS16; MRPS22, MRPS23, MRPS25, MRPS34, MRPS39) and four large ribosomal mitochondrial proteins (MRPL3, MRPL12, MRPL24, MRPL44)." (PMID 36140315, 2022).
cardiovascular disease (1 paper, 2025). "Research suggests that MRPS23 may play an important role in the development of cardiovascular disease." (PMID 40607061, 2025).
infection (1 paper, 2017). The state of being infected such as from the introduction of a foreign agent such as serum, vaccine, antigenic substance or organism. "To validate the efficiency of shMRPS23 knockdown and obtain an appropriate multiplicity of infection (MOI), we examined the expression of MRPS23 in Walker256 cells that were successfully infected with LV-shMRPS23 vectors at a MOI of 1, 5 and 10 respectively." (PMID 29069745, 2017).
MRPS23 also shares sentences with these, for which no sentence is quoted: adrenocortical carcinoma (1 paper); astrocytoma (1); atrial fibrillation (1); breast tumour (1); colon adenocarcinoma (1); endometrial cancer (1); esophageal carcinoma (1); gastric cancer (1); lactic acidosis (1); liver cancer (1); oral squamous cell carcinoma (1); osteosarcoma (1); OXPHOS disease (1); pancreatic cancer (1); pleural mesothelioma (1); Q fever (1); rectum adenocarcinoma (1); Uterine leiomyoma (1).